ABHD8 (abhydrolase domain containing 8)
Description:
Negatively regulates NLRP3-driven inflammation. Promotes NLRP3 degradation through the chaperone-mediated autophagy (CMA) pathway, hence attenuating inflammasome activation and IL1B secretion. Acts by recruiting palmitoyltransferase ZDHHC12 to NLRP3, facilitating NLRP3 palmitoylation and subsequent degradation.
Synonyms: FLJ11743; MGC14280; MGC2512
Tractability: No criterion of Open Targets' tractability assessment is met for any kind of drug.
Gene: Protein-coding gene on chromosome 19 (17,292,131 to 17,310,236, reverse strand). Ensembl gene ENSG00000127220.
Subcellular location: Cytoplasm
Subcellular location (Human Protein Atlas): Nucleoplasm; Nuclear bodies
Gene Ontology:
Molecular function: protein binding; catalytic activity
Biological process: negative regulation of NLRP3 inflammasome complex assembly; phosphatidic acid biosynthetic process
Cellular component: cytoplasm; extracellular exosome
Genetic constraint (gnomAD): Loss-of-function variants: 13 observed, 31.15 expected, observed/expected ratio (o/e) 0.42, 90% interval 0.27 to 0.66. The upper end of that interval is the gene's LOEUF score, 0.66, which puts it in group 2 of 6, group 1 being the genes least tolerant of losing a copy. Missense variants: 556 observed, 623.64 expected, observed/expected ratio (o/e) 0.89, 90% interval 0.83 to 0.96. Synonymous variants: 282 observed, 275.15 expected, observed/expected ratio (o/e) 1.02, 90% interval 0.93 to 1.13.
Homologues: Orthologues: chimpanzee ABHD8 (99% identical), macaque ABHD8 (99% identical), dog ABHD8 (95% identical), pig ABHD8 (95% identical), guinea pig ABHD8 (89% identical), mouse Abhd8 (88% identical), rat Abhd8 (87% identical), tropical clawed frog abhd8 (69% identical), zebrafish abhd8b (63% identical), zebrafish abhd8a (36% identical), Drosophila melanogaster CG11309 (11% identical), Caenorhabditis elegans Y73C8B.3 (10% identical), and 11 more. Paralogues in human: EPHX2 (20% identical), EPHX4 (17% identical), EPHX3 (15% identical), ABHD4 (12% identical), ABHD5 (12% identical), SERHL2 (12% identical), ABHD6 (12% identical), BPHL (12% identical), MEST (10% identical), ABHD11 (10% identical), ABHD14A (9% identical), ABHD14B (9% identical).
Diseases named in the same sentence as ABHD8 in open-access papers:
ABHD8 is named in the same sentence as 9 diseases in open-access papers, as found by Europe PMC text mining. Sharing a sentence is not in itself a finding about the gene and the disease. The quoted sentences say what the papers report.
ovarian carcinoma (3 papers, 2016 to 2020). A malignant neoplasm originating from the surface ovarian epithelium. "Altogether, these data suggest that multiple SNPs at 19p13 regulate ABHD8 and perhaps ANKLE1 expression, and indicate common mechanisms underlying breast and ovarian cancer risk." (PMID 27601076, 2016).
breast carcinoma (1 paper, 2024). "Only one lead variant (rs56069439 of ABHD8) in AA participants showed an association with breast cancer risk at P < 5 × 10−8." (PMID 38697998, 2024).
colorectal cancer (1 paper, 2025). A primary or metastatic malignant neoplasm that affects the colon or rectum. "Among these, genes with positive coefficients (ABHD4, ABHD8, YJEFN3, CRYAB, and HSPA1A) were found to be risk factors, suggesting that their increased expression is associated with worse prognoses in colorectal cancer patients." (PMID 41293172, 2025).
diabetes (1 paper, 2020). "The remaining 2 dysregulated genes—Mmp11 and Abhd8—have not been associated with activities in the brain but have been implicated in diabetes (Mmp11) and lipid metabolism (Abhd8)." (PMID 31912136, 2020).
cancer (5 papers, 2016 to 2025). A tumor composed of atypical neoplastic, often pleomorphic cells that invade other tissues. "This variant has been found to associate with mitochondrial dysfunction and is in very high LD with several variants associated with risk of other cancers, including rs4808616 (r2 > 0.99), a 3’ UTR for ABHD8 linked to breast and lung cancers." (PMID 41038832, 2025). "Up-regulated expressions of the hypo-methylated gDMs in cancer were observed for OAS2, MX2, APOL3, ABHD8, RASSF1, SIGIRR, and SPRED2." (PMID 36329447, 2022). "There are no relevant reports of ZNF79, PRICKLE3, RPAP1, ABHD8, and FBXO33 in cancer, and more research is still needed." (PMID 37274025, 2023).
tumor (2 papers, 2016 to 2025). "For example, under specific microenvironmental cues or in a tumour cell (rather than the normal cells used in these experiments) increased ABHD8 may promote rather than inhibit migration and invasion." (PMID 27601076, 2016).
infection (1 paper, 2020). The state of being infected such as from the introduction of a foreign agent such as serum, vaccine, antigenic substance or organism. "The genes ABHD8, CDO1, RNF125, cell surface hyaluronidase-like, and gopAga1_00017729 were upregulated in medium and severely infected animals relative to control, indicating these may be biomarkers of infection." (PMID 32846428, 2020).
metabolic disorders (1 paper, 2020). "Other genes commonly dysregulated in both SO diets linked to metabolic disorders include Cartpt, Hcrt, Mmp11, and Abhd8 (all upregulated)." (PMID 31912136, 2020).
ABHD8 also shares sentences with these, for which no sentence is quoted: Granuloma (1 paper).